PALLD (palladin, cytoskeletal associated protein)
Description:
Cytoskeletal protein required for organization of normal actin cytoskeleton. Roles in establishing cell morphology, motility, cell adhesion and cell-extracellular matrix interactions in a variety of cell types. May function as a scaffolding molecule with the potential to influence both actin polymerization and the assembly of existing actin filaments into higher-order arrays. Binds to proteins that bind to either monomeric or filamentous actin. Localizes at sites where active actin remodeling takes place, such as lamellipodia and membrane ruffles. Different isoforms may have functional differences. Involved in the control of morphological and cytoskeletal changes associated with dendritic cell maturation. Involved in targeting ACTN to specific subcellular foci.
Synonyms: KIAA0992; CGI-151; SIH002; CGI151; MYN; PNCA1
Tractability: Antibody: its Gene Ontology location is reachable by antibodies, with high confidence. PROTAC: ubiquitination databases record sites on it; its protein half-life has been measured.
Gene: Protein-coding gene on chromosome 4 (168,497,052 to 168,928,457, forward strand). Ensembl gene ENSG00000129116.
Subcellular location: Cytoplasm, cytoskeleton; Cell junction, focal adhesion; Cytoplasm, myofibril, sarcomere, Z line; Cell projection, ruffle; Cell projection, podosome; Cell projection, lamellipodium; Cell projection, axon; Cell projection, growth cone
Subcellular location (Human Protein Atlas): Actin filaments; Cytosol; Mitochondria; Plasma membrane
Gene Ontology:
Molecular function: protein binding; cell-cell adhesion mediator activity; muscle alpha-actinin binding
Biological process: axon guidance; cytoskeleton organization; dendrite self-avoidance; homophilic cell-cell adhesion; actin cytoskeleton organization; cell migration
Cellular component: actin cytoskeleton; actin filament; cytosol; focal adhesion; lamellipodium; nucleus; stress fiber; Z disc; axon; excitatory synapse; plasma membrane; cytoskeleton; growth cone; podosome; ruffle
Genetic constraint (gnomAD): Loss-of-function variants: 45 observed, 89.54 expected, observed/expected ratio (o/e) 0.5, 90% interval 0.4 to 0.64. The upper end of that interval is the gene's LOEUF score, 0.64, which puts it in group 2 of 6, group 1 being the genes least tolerant of losing a copy. Missense variants: 1,063 observed, 1,216.1 expected, observed/expected ratio (o/e) 0.87, 90% interval 0.83 to 0.92. Synonymous variants: 403 observed, 447.32 expected, observed/expected ratio (o/e) 0.9, 90% interval 0.83 to 0.98.
Homologues: Orthologues: chimpanzee PALLD (99% identical), macaque PALLD (97% identical), rabbit PALLD (89% identical), mouse Palld (88% identical), rat Palld (87% identical), guinea pig PALLD (87% identical), pig PALLD (79% identical), tropical clawed frog palld (65% identical), zebrafish palld (57% identical), Caenorhabditis elegans unc-22 (28% identical), Drosophila melanogaster bt (16% identical), Caenorhabditis elegans dim-1 (7% identical). Paralogues in human: MYPN (44% identical), SPEG (24% identical), HMCN1 (24% identical), OBSCN (21% identical), IGFN1 (15% identical), ALPK3 (14% identical), MYOT (14% identical), CCDC141 (12% identical), SPEGNB (6% identical).
Diseases named in the same sentence as PALLD in open-access papers:
PALLD is named in the same sentence as 28 diseases in open-access papers, as found by Europe PMC text mining. Sharing a sentence is not in itself a finding about the gene and the disease. The quoted sentences say what the papers report.
pancreatic cancer (8 papers, 2012 to 2025). "Mutations in the PALLD gene have been linked to pancreatic cancer, and PALLD levels have been shown to correlate with increased invasiveness of cancer cells." (PMID 36927816, 2023). "We identified a family with pancreatic cancer with a germline mutation of PALLD, located in a pancreatic cancer susceptibility locus at 4q32-34, in 2 sibling patients suffering from pancreatic cancer, whereas 2 healthy siblings were not carrying the mutation." (PMID 33764904, 2021). "The identical germline mutation of the PALLD gene (NM_001166108.1:c.G154A:p.D52N) was detected in the index patient with pancreatic cancer and the tumor tissue of her sister." (PMID 33764904, 2021). "Germline heterozygous variants in the PALLD gene have only been described in a few families with susceptibility to pancreatic cancer (OMIM #606856,)." (PMID 29373990, 2018). "Germline mutations in PALLD have been reported in high-risk pancreatic cancer families." (PMID 37762649, 2023). "Linkage of PALLD mutations to familial pancreatic cancers is controversial." (PMID 23152778, 2012). "Rescue experiments overexpressing PALLD in shSTAU2 cell lines validated the regulatory role of the STAU2‐PALLD‐EMT axis in pancreatic cancer cell migration, invasion, and EMT pathway expression." (PMID 40539383, 2025). "PALLD promotes pancreatic cancer cell invasion by promoting the invasive formation of tumor-associated fibroblasts." (PMID 35892886, 2022). "Previous studies have shown increased PALLD expression in CAFs of pancreatic tumors and other invasive tumor types, suggesting a role in tumor aggressiveness and invasiveness." (PMID 33764904, 2021).
breast carcinoma (3 papers, 2016 to 2023). "In this study we initially identified a common functional variant, rs1071738, at the miR-96 and miR-182 target site on the PALLD 3′-UTR, that we thought may potentially influence breast cancer metastasis." (PMID 27641360, 2016). "Extensive panel testing covering more than 40 genes is being increasingly marketed, but the diagnostic yield and action-ability remains questionable particularly for candidate genes such as TSC2 / PALLD which may not be relevant to patients with suspected hereditary breast cancer." (PMID 30875412, 2019).
dilated cardiomyopathy (3 papers, 2023 to 2025). Cardiomyopathy which is characterized by dilation and contractile dysfunction of the left and right ventricles. "Dysregulation of PALLD (palladin), a component of actin-containing microfilaments, has been associated with myocardial infarction and dilated cardiomyopathy." (PMID 39803589, 2024). "Conversely, PALLD, a cytoskeletal protein, was significantly downregulated in both datasets, implicating its reduction in intercalated disc dysfunction and dilated cardiomyopathy." (PMID 40607964, 2025). "(C) Quantitative real-time PCR (qRT-PCR) analysis for MYPN, PALLD, and ANKRD1 on LV biopsies from dilated cardiomyopathy (DCM) (n = 15) and ischemic cardiomyopathy (ICM) (n = 15) male patients vs." (PMID 36927816, 2023).
ischemic cardiomyopathy (3 papers, 2021 to 2024). Ischemic cardiomyopathy is a cardiomyopathy in which a weakness in the muscle of the heart due to inadequate oxygen delivery to the myocardium with coronary artery disease being the most common cause. "In this study, we analyzed the immune infiltration profiles of CM and NF samples, and identified CALU and PALLD as potential diagnostic biomarkers for heart failure due to ischemic cardiomyopathy by using integrated bioinformatics analyses." (PMID 34926621, 2021). "Altered transcript levels of MYPN and PALLD isoforms were found in myocardial tissue from human dilated and ischemic cardiomyopathy patients, whereas their protein expression levels were unaltered." (PMID 36927816, 2023). "Although the role of the PALLD gene in Temra cells remains unknown, it acts as a biomarker in heart-infiltrating immune cells of patients with ischemic cardiomyopathy." (PMID 38370415, 2024). "Similarly, in two RNA-Seq studies, PALLD was reported to be downregulated in both DCM/non-ischemic cardiomyopathy (NICM) (~1.7- to ~2.0-fold) and ICM (~1.6- to ~2.1-fold) patients, while MYPN was upregulated in both DCM/NICM (~1.5- to ~1.6-fold) and ICM (~1.6- to ~1.7-fold) patients." (PMID 36927816, 2023). "Quantitative real-time PCR (qRT-PCR) analyses on myocardial tissue from DCM and ischemic cardiomyopathy (ICM) patients showed increased transcript levels of MYPN and the PALLD long isoform in DCM patients, while total transcript levels of PALLD were reduced in both DCM and ICM patients." (PMID 36927816, 2023).
prostate carcinoma (3 papers, 2010 to 2025). A carcinoma that arises from epithelial cells of the prostate gland. "Our findings provide strong evidence that PALLD plays a critical role in promoting the proliferation and colony-forming ability of prostate cancer cells." (PMID 40002724, 2025). "As a mitochondria-associated gene, PALLD has not been previously studied in prostate cancer." (PMID 40002724, 2025). "Knockdown of PALLD significantly inhibits the proliferation and colony-forming ability of PC3 and DU145 cells, suggesting the important roles of this gene in prostate cancer progression." (PMID 40002724, 2025). "In prostate cancer cell lines, CAV1, PALLD, and ITGB8 are upregulated, while CLDN7 is downregulated." (PMID 40002724, 2025). "The expression levels of CAV1, PALLD, ITGB8, and CLDN7 were analyzed using RT-qPCR in the normal prostate epithelial cell line RWPE1 and four prostate cancer cell lines: LNCaP, 22RV1, DU145, and PC3." (PMID 40002724, 2025). "The best three single gene discriminators are MYLK, PALLD and CAV1 for prostate cancer, having 73.4%, 71.9% and 71.1% classification accuracy on the training set and 83.5% and 62.3%, 69.6% and 72.6%, and 94.2% and 75.5% on the two test sets, respectively." (PMID 21060876, 2010). "Since PALLD has not been previously reported in prostate cancer, we further tested its function in vitro." (PMID 40002724, 2025).
myocardial infarction (2 papers, 2020 to 2023). Gross necrosis of the myocardium, as a result of interruption of the blood supply to the area, as in coronary thrombosis. "Corroborating these findings, one of the top genes associated with AP identified in this study, PALLD, has been previously reported to have variants associated with increased risk of pancreatic cancer type 1 and myocardial infarction." (PMID 36747740, 2023). "For example, genetic variants of PALLD (palladin, cytoskeletal associated protein), important for organizing actin cytoskeleton, have been reported to be associated with myocardial infarction." (PMID 32423033, 2020).
cardiomyopathies (1 paper, 2023). "MYPN gene mutations are associated with human cardiomyopathies, whereas the role of PALLD in the heart has remained unknown, partly due to embryonic lethality of PALLD knockout mice." (PMID 36927816, 2023). "Based on its similarity to MYPN, associated with different forms of cardiomyopathy, as well as high expression levels of specific PALLD isoforms in cardiac muscle both during development and at adult stage, we hypothesized that PALLD plays an important role also in the heart." (PMID 36927816, 2023). "Altogether, our data demonstrate an important role of PALLD for normal heart function, suggesting PALLD as a possible candidate gene for cardiomyopathy." (PMID 36927816, 2023).
glioma (1 paper, 2022). A benign or malignant brain and spinal cord tumor that arises from glial cells (astrocytes, oligodendrocytes, ependymal cells). "Overexpression of PALLD in glioma tumors compared to non-tumor samples was also validated in six of the seven datasets containing non-tumor samples in the GlioVis website." (PMID 36291914, 2022).
heart failure (1 paper, 2021). Inability of the heart to pump blood at an adequate rate to meet tissue metabolic requirements. "We found that the expression trends of CALU and PALLD in GSE116250 were consistent with those in GSE5406, and that CALU and PALLD also had high accuracy in classifying heart failure samples, as evidenced by AUC >0.7." (PMID 34926621, 2021). "To get the robust gene signature in heart failure, we overlapped genes from LASSO and SVM-RFE and got six gene signatures, including PALLD, DDX39A, CD164, CLDND1, SLC38A2, and CALU." (PMID 34926621, 2021).
lupus nephritis (1 paper, 2026). Glomerulonephritis in the context of systemic lupus erythematosus. "In lupus nephritis, MKL1, MKL2, and SRF also negatively correlated with GFR, and PALLD was shown to negatively correlate with GFR." (PMID 41131992, 2026). "Interestingly, PALLD was strongly correlated with MKL1, MKL2, and SRF in human lupus nephritis samples." (PMID 41131992, 2026).
metastatic cancer (1 paper, 2025). A carcinoma which has spread from the original site of growth to another anatomic site. "The results showed that the expression levels of CLOCK, along with CBX5, CHN1, CNN3, FNDC1, PALLD, and SULF1, were significantly elevated in metastatic cancer tissues compared to primary cancer tissues." (PMID 41350567, 2025).
Obesity (1 paper, 2016). Accumulation of substantial excess body fat. "Furthermore, a link between PALLD (palladin, cytoskeletal associated protein) and obesity has been reported." (PMID 27019061, 2016).
oligoastrocytoma (1 paper, 2022). A WHO grade II tumor composed of a conspicuous mixture of two distinct neoplastic cell types morphologically resembling the tumor cells in oligodendroglioma and diffuse astrocytoma. "The highest levels of PALLD expression were found in astrocytoma tumors, followed by oligoastrocytoma, and, finally, oligodendroglioma tumors." (PMID 36291914, 2022).
osteosarcoma (1 paper, 2017). A usually aggressive malignant bone-forming mesenchymal neoplasm, predominantly affecting adolescents and young adults. "As U2OS (osteosarcoma cell line) is recognized as another classic model for mitosis research, we performed spindle orientation assay and confirmed that PALLD depletion also led to spindle misorientation in U2OS cells." (PMID 28924223, 2017).
Stroke (1 paper, 2021). Sudden impairment of blood flow to a part of the brain due to occlusion or rupture of an artery to the brain. "In addition, PALLD gene polymorphisms were found to be associated with stroke." (PMID 32980981, 2021).
cancer (12 papers, 2010 to 2025). A tumor composed of atypical neoplastic, often pleomorphic cells that invade other tissues. "PALLD expression is intricately linked to the malignant cell motility characteristics exhibited by aggressive cancer cells." (PMID 40226355, 2025). "Palladin (PALLD), an actin-associated protein whose expression is intimately linked to the pathogenic cell motility properties of aggressive cancer cells, is encoded by the PALLD gene." (PMID 34925466, 2021). "As an actin-binding and microfilament-associated protein, PALLD has been reported to regulate cell morphology, mobilization, adhesion, invasion, and metastasis of cancer cells." (PMID 28924223, 2017). "Hypermethylation of the GSTP1 promoter has also been previously reported as having association with prognostic values, and repression of PALLD gene has been shown to contribute to invasive motility and cancer cell migration." (PMID 28155687, 2016). "Importantly, similar to previous reports defining cancer-associated fibroblasts (CAFs), such fibroblasts expressed PALLD, which appeared to be more prominent than in the adjacent and distant normal pancreatic tissue." (PMID 33764904, 2021). "In contrast, CBX3, CHN1, SULF1 and VDAC1 were significantly elevated in SKCM compared to HD samples, while EDIL3 and PALLD demonstrated significantly lower expression levels in the cancer samples." (PMID 41350567, 2025). "Knockdown of PALLD expression in PC3 and DU145 cell lines led to a significant reduction in both cell proliferation and colony formation, indicating that PALLD is essential for maintaining the growth and survival of these cancer cells." (PMID 40002724, 2025). "PALLD is well-known for its involvement in cell motility and smooth muscle cell differentiation, implicating it in cancer, while its role in the heart has remained elusive, in part due to embryonic lethality of PALLD knockout mice." (PMID 36927816, 2023). "Among cancer cell lines, a wide array of tissues giving rise to carcinomas did show robust PALLD expression, with a major gap only appreciated between hematological malignancies and all others." (PMID 33764904, 2021). "In combination with previous significant linkage and functional analysis data suggesting that PALLD mutations cause FPC, the PALLD gene was selected as the most likely cancer-causing alteration in this family." (PMID 33764904, 2021). "A third example is the PALLD gene which has been found in 75 cancer experiments and whose probe sets (2751068 and 2751072) were identified by REIDS to be up-regulated in heart, muscle, thyroid and prostate, but down-regulated in the other tissues." (PMID 28545391, 2017). "PALLD is overexpressed in strongly aggressive cancer cells, so dysregulation of PALLD may promote invasive/invasive pathological behavior of cancer cells." (PMID 40002724, 2025). "Furthermore, PALLD is responsible for cell morphology, mobilization, adhesion, invasion and metastasis of cancer cells." (PMID 28924223, 2017). "Furthermore, these findings align with previous studies implicating cytoskeletal regulators, such as PALLD, in cancer progression and metastasis, reinforcing the idea that modulating the actin cytoskeleton may offer a promising strategy for cancer therapy." (PMID 40002724, 2025).
tumor (7 papers, 2018 to 2022). "Having confirmed an inherited PALLD mutation, we further performed whole genome sequencing to better compare the sibling tumor sequences." (PMID 33764904, 2021). "Since PDAC is characterized by a strong desmoplastic reaction that creates a dense microenvironment and epithelial-mesenchymal transition (EMT), the PALLD mutation might promote tumor-stromal interactions, leading to tumor invasiveness and metastasis." (PMID 33764904, 2021). "Nevertheless, this study provides evidence that PALLD is a pancreatic cancer susceptibility gene, likely through the presence of an abnormal palladin gene in stromal CAFs, therefore defining a carcinogenic tumor microenvironment that favors distinct mutagenic alteration in pancreatic ductal cells." (PMID 33764904, 2021). "However, malignant ductal cells could also express PALLD at high levels, suggesting that its expression is associated with a more dedifferentiated — and, thus, more aggressive — tumor." (PMID 33764904, 2021). "We identified eight tumor types with significant PALLD overexpression relative to healthy tissue: bile duct, brain, breast, liver, lung, pancreas, stomach, and thyroid." (PMID 36291914, 2022). "In all three datasets, PALLD expression was significantly greater in tumor than non-tumor samples." (PMID 36291914, 2022). "PALLD mRNA levels differed significantly between tumor types (HKruskal–Wallis = 90.08, p < 0.0001)." (PMID 36291914, 2022). "In our compartment-specific gene expression data from precursor lesions and PDAC specimen, PALLD expression was mostly upregulated in CAFs, supporting the concept that PALLD indeed promotes tumor–stromal interactions, leading to tumor invasiveness and metastasis." (PMID 33764904, 2021). "However, PALLD expression does occur in malignant ductal cells at high levels, which correlate with a dedifferentiated, more aggressive class of tumors, consistent with cell-autonomous, tumor-promoting qualities of PALLD." (PMID 33764904, 2021). "Meanwhile, the expression of PALLD and GEMIN2 in the tumor was obviously lower than that in tumor-adjacent tissue." (PMID 36421795, 2022).
cardiac disease (1 paper, 2023). "The reason why a putative link between PALLD mutations and cardiac disease has not been established could be due to lack of focus on the PALLD gene." (PMID 36927816, 2023). "Our findings demonstrating an important role of PALLD for normal cardiac function prompted us to determine whether transcript levels of PALLD and its striated muscle-specific homologue MYPN are altered during ischemic and nonischemic cardiac disease." (PMID 36927816, 2023).
PALLD also shares sentences with these, for which no sentence is quoted: bladder cancer (2 papers); diabetes (2); Constipation (1); hypertrophic cardiomyopathy (1); lissencephaly type 2 (1); oligodendroglioma (1); ovarian carcinoma (1); Sneddon syndrome (1); type 2 diabetes mellitus (1); virus infection (1).